CTLA4 (cytotoxic T-lymphocyte associated protein 4)
Diseases named in the same sentence as CTLA4 in open-access papers (continued):
Sharing a sentence is not in itself a finding about the gene and the disease.
tumor (continued). "Targeting SPINK5-mediated immune suppression to restore anti-tumor immunity could improve the effectiveness of immune checkpoint therapies, including anti-PD-1/PD-L1 and anti-CTLA-4 treatments." (PMID 40872585, 2025). "While the reason for this difference is unknown, it is worth noting that the two types of ICI therapies, namely anti-PD1/PD-L1 and anti-CTLA-4, are thought to function quite differently within the tumor tissue." (PMID 41439026, 2025). "Additionally, NF-κB enhances the expression of immune checkpoint molecules (such as PD-L1 and CTLA-4), aiding tumor cells in evading immune surveillance." (PMID 40563359, 2025). "Moreover, in tumor-infiltrating regulatory T cells (Tregs), USP39 has been identified to increase RNA splicing-mediated CTLA-4 expression, which in turn enhances the immunosuppressive function of Tregs, thereby suppressing anti-tumor immunity." (PMID 40990019, 2025). "Likewise, ICOS and CTLA4 are primarily expressed by T cells, but are significantly higher in expression in tumour compared to pancreatic adjacent normal tissue in epithelial and endothelial cells." (PMID 39915477, 2025). "In addition, immune checkpoint molecules PD-1 (PDCD1), PD-L1 (CD274), and CTLA4 mediate tumor immune escape by suppressing the activity of immune cells and are known potential targets for RC immunotherapy." (PMID 40963625, 2025). "A previous study showed that an OV expressing hPD-1scFv could safely and effectively enhance systemic anti-tumor immunity by boosting T cells and overcoming local immunosuppression to make tumors more responsive to CTLA-4 or TIM-3 blockade." (PMID 40821119, 2025). "Moreover, adding entinostat and azacytidine significantly reduced tumor-infiltrating FoxP3+ Tregs compared to untreated or anti-PD-1/CTLA-4 antibody-only groups." (PMID 41024300, 2025). "are essential for the anti-tumor effects of anti-CTLA-4 therapy." (PMID 41228220, 2025). "Similar patterns were detected in human tumor samples along with expression of additional immunoregulatory molecules such as CTLA-4, TIM-3 and CD137 (4-1BB) that could be detected on more T cells in the tumor than in the periphery." (PMID 39751916, 2025). "Importantly, the analysis for tumor-infiltrating T lymphocytes in P4 tumors demonstrated enhanced expression of the immune checkpoint inhibitor CTLA4, while those in P1 demonstrated a higher frequency of the effector Th17/Th1 phenotype." (PMID 40563574, 2025). "Expression of CTLA-4 was identified in 96% of tumor samples (n = 46)." (PMID 40416849, 2025). "Elevated ORAOV1 expression correlates strongly with aggressive clinicopathological features and promotes an immunosuppressive tumor microenvironment characterized by increased infiltration of pro-tumor immune cells and elevated expression of immune checkpoints such as CTLA4, PD1, and PD-L1." (PMID 41321947, 2025). "Therefore, the immune checkpoint blockades (ICBs), anti-CTLA-4 and anti-PD-L1, can enhance antitumor immunity through disrupting the tumor co-inhibitory immune cells." (PMID 40017598, 2025). "Additionally, GREM1 contributes to T cell exhaustion by upregulating immune checkpoints like CTLA-4 and PD-1 and overactivating key signaling pathways, thereby impairing antitumor immunity and accelerating tumor progression." (PMID 40066442, 2025). "Immune checkpoints, particularly cytotoxic T-lymphocyte antigen-4 (CTLA-4), play a pivotal role in regulating the immune response and may influence tumor progression and treatment response." (PMID 40861696, 2025). "Notably, single-cell TCR sequencing confirms that CTLA-4 inhibitors combined with PD-1 blockade synergistically enhance T-cell clone spatiotemporal dynamics, significantly improving anti-tumor immunity breadth and durability." (PMID 41425703, 2025). "Moreover, tumor-infiltrating Tregs were functionally impaired as reflected by reduced CTLA4 expression." (PMID 39979425, 2025).
tumor (continued). "However, in some tumor microenvironments, the anti-tumor immune response is inhibited by upregulation of PD-L1 or CTLA-4 expression." (PMID 39141277, 2025). "CTLA-4 inhibitors expand the diversity of the initial T cell pool and enhance the anti-tumor immune response by targeting the co inhibitory signal at the early T cell activation stage and destroying the competitive inhibition of the CD28 co-stimulatory pathway." (PMID 41425703, 2025). "Targeting molecules involved in Treg function, such as CTLA-4, can enhance anti-tumor immune responses, and combining checkpoint inhibitors with other therapies may further enhance anti-tumor immunity." (PMID 40475782, 2025). "In addition, a tumor microenvironment-activated nanoassembly that PD-L1 and CTLA-4 antagonistic aptamers are synthesized and co-assembly with glucose transporter 1 inhibitors has been demonstrated to significantly reduce PD-L1 N-linked glycosylation." (PMID 40087690, 2025). "LTX-315 plus an anti-CTLA-4 antibody could synergistically improve the immunosuppressive microenvironment in residual tumors and induce a strong anti-tumor immunity after iRFA of HCC." (PMID 40222972, 2025). "Immunotherapy has significantly transformed the therapeutic landscape in modern oncology, with immune checkpoint inhibitors (ICIs) such as anti-PD-1, anti-PD-L1, and anti-CTLA4 emerging as established standards of care for various tumor types, particularly at advanced stages." (PMID 40108446, 2025). "Thus, only the less activated CD8 T cells in the tumor have Cd28 expression that is unopposed by Ctla4." (PMID 41417245, 2025). "In a model of triple-negative breast cancer (TNBC), OAds demonstrated a synergistic effect when combined with anti-PD-L1 and anti-CTLA-4 immunotherapies, resulting in improved tumor control and extended survival, with 20% of the subjects exhibiting complete suppression of metastasis." (PMID 40698086, 2025). "Additionally, ALM tumors tend to harbor fewer tumor-infiltrating lymphocytes, critical for the efficacy of immune checkpoint inhibitors such as anti-PD-1 and anti-CTLA-4." (PMID 39941835, 2025). "Furthermore, both PD-L1 knockout and ZG16 overexpression in cancer cells can target PD-L1 and CTLA4 within the tumor immune microenvironment." (PMID 39958358, 2025). "This combination therapy leverages the dual mechanisms of immune checkpoint inhibition, where ipilimumab targets and blocks CTLA-4 to boost T-cell activity, while nivolumab inhibits PD-1, together creating a synergistic enhancement of the anti-tumor immune response." (PMID 39833954, 2025). "Furthermore, the blockade of CXCL12-CXCR4 axis along with anti-PD-1 and anti-CTLA-4 ICB therapies promises anti-tumour responses in colon cancer, emphasising the importance of combination therapies." (PMID 40852716, 2025). "Following nine cycles of cadonilimab, a novel PD-1/CTLA-4 bispecific antibody, the patient achieved significant tumor regression and subsequent pathological complete response (pCR) after surgery, with a favorable safety profile observed throughout the treatment course." (PMID 41561746, 2025). "This consistency can be biologically explained by the complementary mechanisms of dual immune checkpoint blockade: PD-1/PD-L1 inhibition restores cytotoxic T-cell activity, while CTLA-4 inhibition enhances T-cell priming and broadens the tumor-infiltrating lymphocyte repertoire." (PMID 41479494, 2025). "In CRC mice treated with anti-CTLA-4 and Lactobacillus acidophilus lysates, tumor reduction was associated with increased IL-2, IFN-γ, and CD8+ T cell infiltration, with Bifidobacterium upregulating tumor-specific CD8+ T cells and IFN-γ secretion." (PMID 39996827, 2025). "Interestingly, complete tumor regression was observed with anti-CTLA-4 antibody therapy, even in ULBP2-expressing tumors, suggesting that immune suppression induced by ULBP2 can be overcome under certain conditions." (PMID 40558520, 2025).
tumor (continued). "Tumor cells can also obtain the immunoregulatory proteins CTLA4 and Tim3 from immune cells." (PMID 40723152, 2025). "We next performed anti-CTLA-4 therapy in tumor-bearing mice depleted of CD4+ T cells." (PMID 40460830, 2025). "For example, for an immunotype with a pronounced pro-tumor profile in cancer, we can use immunotherapy, taking into account its unique features (such as the expression levels of specific molecules like CTLA-4, PD-1, Lag-3, etc. or need in monocytes reprogramming)." (PMID 40948783, 2025). "This unique mechanism allows CTLA‐4 to act as an effector molecule by depleting co‐stimulatory ligands extracellularly, thereby increasing activation threshold and dampening responses to weak antigens, including tumour antigens and autoantigens." (PMID 40415479, 2025). "RP-2 is an enhanced-potency, HSV-1-based OV with the addition of GALV-GP-R- (enhances cell fusion and tumor lysis), an anti-CTLA4 antibody-like molecule (improves T-cell priming and activation), and a codon-optimized sequence of GM-CSF (for recruiting and activating DCs)." (PMID 40733704, 2025). "When administered 7 days before RT, anti‐CTLA‐4 led to complete tumor regression and 100% survival." (PMID 40900811, 2025). "While PD-1 and PD-L1 blocking antibodies enhance the activity of cytotoxic T lymphocytes (CD8+ T cells) in peripheral tissues and inside tumours, CTLA-4-blocking antibodies activate CD8+ T cells and suppress the activity of Tregs in the initial T cell activation stage." (PMID 41462864, 2025). "Additionally, its immunomodulatory effects on the tumor microenvironment (TME) establish a theoretical foundation for combination with PD-1/PD-L1 or CTLA-4 inhibitors, potentially overcoming immune tolerance in certain patients." (PMID 40599859, 2025). "Another relevant bsAb, QL1706, which combines an anti-PD-1 antibody with an anti-CTLA-4 antibody, has shown anti-tumor activity in advanced solid tumors, including NSCLC, with an improved tolerability profile due to pharmacokinetic optimization and reduced irAEs." (PMID 41303538, 2025). "For example, studies using murine models have shown that the combination of CTLA-4 blockade and radiation therapy results in improved tumor control and enhanced immune responses, suggesting this combination may be effective in treating various cancers." (PMID 40170852, 2025). "Additionally, trogocytosis enables the acquisition of immune-regulatory molecules, such as CTLA-4 and Tim3, in recipient cells, thereby modulating their anti-tumor immunity." (PMID 39741180, 2025). "Similarly, CTLA4 and PD-1 are key negative regulators of T-cell activation, and their upregulation can lead to immune tolerance and tumor progression." (PMID 40561678, 2025). "Notably, combining PLA2G7 depletion with CTLA-4 blockade significantly improved the suppression of tumor burden and mouse survival rates." (PMID 40169540, 2025). "The core hypothesis is that PD-1/CTLA-4 dual blockade can enhance tumor antigen-specific T cell responses and inhibit regulatory T cell (Tregs) function, synergizing with the immunomodulatory effects of AG chemotherapy to overcome PDAC treatment resistance." (PMID 41142819, 2025). "Moreover, ongoing trials are exploring combinations with other immune checkpoint inhibitors, such as CTLA-4 inhibitors, to further enhance the anti-tumor immune response and overcome resistance mechanisms in tumors that evade immune detection." (PMID 40061961, 2025). "Furthermore, the combo of radiation, hu14.18-IL.2, and anti-CTLA-4 improved animal survival and reduced the burden of tumor metastases compared to the use of radiation and immunocytokines." (PMID 39852848, 2025). "Preliminary investigative findings in preclinical research suggest that cadonilimab’s selective accumulation within tumor tissues, in contrast to standard anti-PD-1 and anti-CTLA-4 antibodies, may contribute to an enhanced safety profile." (PMID 40746596, 2025).
tumor (continued). "PD-1 and PD-L1 checkpoints suppress T-cell activation and anti-tumor responses, while CTLA-4 inhibits initial T-cell activation in lymph nodes by competing with CD28 for B7 ligands on antigen-presenting cells (APCs), thereby fostering anergy and enhancing the function of Tregs." (PMID 41239350, 2025). "Concurrently, lymphocytes that infiltrate the tumor often show increased levels of immune checkpoint proteins, including lymphocyte-activation gene 3 (LAG-3), cytotoxic T-lymphocyte-associated protein 4 (CTLA-4), and programmed death 1 (PD-1)." (PMID 40805123, 2025). "Additionally, patients with high ICAFBS score showed enhanced expression of multiple immune checkpoint molecules, including PD‐1, PD‐L1, and CTLA‐4, indicating a tumor milieu prone to immune evasion." (PMID 41395115, 2025). "A high primary tumor expression of CTLA4 identifies patients with an excellent prognosis, for whom standard chemotherapy may be de-escalated or omitted." (PMID 40523912, 2025). "Notably, in groups receiving TTFields alongside anti-PD-1/anti-CTLA-4 or anti-PD-L1, there was a pronounced increase in immune cell infiltration, particularly cytotoxic T cells, into the tumor microenvironment." (PMID 40835706, 2025). "Therefore, CTLA-4 prevents uncontrolled expansion of activated T cells, favoring the expansion of regulatory T cells (Tregs) over helper T cells, thus generating a tumor immunosuppressive effect." (PMID 41415542, 2025). "Anti-CTLA-4 antibodies enhance anti-tumor effects of CD4+ and CD8+ T lymphocytes." (PMID 40607438, 2025). "Indeed, use of the addition of anti–CTLA-4 antibody therapy to CAN-2409 treatment resulted in better controlled tumor growth compared with CAN-2409 treatment alone." (PMID 39881590, 2025). "CTLA-4 has been proposed as an alternative target for cancer immunotherapy, with the hypothesis that blocking CTLA-4 could enhance the immune system's ability to recognize and attack tumor cells." (PMID 40693234, 2025). "Additionally, TGF-β1 increases the PD-1 and CTLA-4 levels via the calcium-regulated phosphatase nuclear factor of activated T cells 1 (CaN/NFATc1) pathway, aiding tumor immune evasion." (PMID 40723175, 2025). "Given the immunosuppressive nature of PDAC, combining Gal-3 inhibition with anti-PD-1 or anti-CTLA-4 therapies could enhance anti-tumor immunity." (PMID 41153387, 2025). "The simultaneous administration of MUC1 mRNA and CTLA-4-targeting siRNA represents a dual immunotherapeutic strategy aimed at overcoming the immunologically “cold” tumor microenvironment characteristic of TNBC, a context in which such combined approaches have been explored only to a limited extent." (PMID 40943370, 2025). "The emergence of autoreactive B cells following CTLA-4 blockade includes clones that may recognize self antigens expressed in tissues affected by irAEs but also tumor neo- or self antigens and thereby promote antitumor responses." (PMID 41026527, 2025). "The upregulation of PD-1 indicates T cell activation in the tumour microenvironment, while co-expression of CTLA-4 and TIM-3 may suggest T cell exhaustion." (PMID 40639721, 2025). "Notably, PD‐1 and CTLA‐4 were predominantly expressed by tumour‐infiltrating T lymphocytes, while PD‐L1 was primarily expressed by tumour‐associated macrophages." (PMID 39789732, 2025). "Refinement of biomarker assessment—including co-expression of cytotoxic T-lymphocyte-associated protein 4 (CTLA-4), Lymphocyte Activation Gene 3 (LAG3), or tumor mutational burden (TMB) status—may help identify responders more accurately." (PMID 40881855, 2025). "Cisplatin can augment anti-tumor immune responses in combination with immune checkpoint blockers (such as PD-1/PD-L1 or CTLA4 inhibitors), lipid metabolism disruptors (like FASN inhibitors and SCD inhibitors) and nanoparticles (NPs), resulting in better outcomes." (PMID 39757995, 2025).
tumor (continued). "Also, while not differentially expressed, the important immune checkpoints PDCD1 (PD1) and CTLA4 were present in all tumor samples." (PMID 40149290, 2025). "Animal studies suggest that KMT may reduce the expression of PD-1, CTLA-4, and their ligands on tumor-infiltrating cells." (PMID 40585643, 2025). "Combining FolTAC-dual with immune adjuvants or checkpoint inhibitors, such as anti-CTLA-4, may further mitigate this effect and enhance anti-tumor immunity." (PMID 41038820, 2025). "Moreover, the high expression of immune checkpoint molecules—such as programmed cell death protein 1 (PD-1), its ligand PD-L1, and cytotoxic T lymphocyte-associated antigen 4 (CTLA-4)—further induces CTL exhaustion, limiting their tumor-clearing capacity." (PMID 41280655, 2025). "Furthermore, we found that effector CD4+ T cells, particularly Tbet+ICOS+ Th1-like CD4+ T cells, were important for the remodeling of tumor vasculature and the increase of TA-HEVs during anti-CTLA-4 therapy in the MCAprog tumor model." (PMID 40460830, 2025). "Next, we assessed whether the Akt inhibitor could improve the anti-tumor effects of RT or a combined blockade of PD-L1 and CTLA-4 (αPD-L1/αCTLA-4)." (PMID 41378083, 2025). "CD4+ T-cell-derived IFNγ could increase microglial MHCII expression, as observed in our analysis, and then promote microglial phagocytosis of GBM tumor, in a way resembling the report of anti-CTLA-4 treatment." (PMID 39885128, 2025). "In paraffin samples (all DIPG), we found PD-L1+ cells only in 1 tumor of 16 analyzed (the positive tumor was the only one without H3 mutation in the series) and scarse CTLA-4+ cells in 14 of 18 tumors." (PMID 40703808, 2025). "The landmark discovery of the cytotoxic T lymphocyte-associated protein 4 (CTLA-4/B7-1) and programmed cell death ligand-1/programmed cell death protein-1 (PD-L1/PD-1) interactions are pivotal advancements in tumor immunotherapy, propelling extensive research endeavors into immune checkpoints." (PMID 40343258, 2025). "Furthermore, a mouse model has shown that the targeted elimination of Ctla4+ Treg cells results in complete tumor remission." (PMID 41019045, 2025). "Key pathways are VEGF and HIF-α, which are pivotal in promoting angiogenesis and ensuring the tumor’s blood supply, and CTLA-4 and PD-1/PD-L1 pathways, which are central to immune checkpoint regulation and enable tumors to evade immune surveillance by inhibiting T cell activity." (PMID 41020852, 2025). "CTLA-4 exhibits inhibitive capacity and can ease tumor evasion." (PMID 40565233, 2025). "CTLA-4 inhibition (e.g., ipilimumab, tremelimumab) enhances early T-cell priming, but a concise immunologic summary highlights that dual blockade broadens T-cell activation across multiple stages of the anti-tumor response." (PMID 41479494, 2025). "Expectedly, anti‐CTLA‐4 therapy suppressed the tumor growth of 4T1 cells in vivo." (PMID 39912421, 2025). "By abrogating inhibitory signaling on T lymphocytes—particularly via blockade of PD-1/PD-L1 or CTLA-4 interactions—ICIs potentiate cytotoxic immune responses, thereby enhancing lymphocyte-mediated tumor eradication and markedly improving clinical outcomes in patients with advanced malignancies." (PMID 41200174, 2025). "Here the authors report the results of a phase II clinical trial of anti-PD1 nivolumab plus anti-CTLA4 ipilimumab in RMC, associating the activation of a myeloid mimicry program in tumor cells to the rapid disease progression and hyper-progression observed in treated patients." (PMID 41290625, 2025). "Also, in the anti-tumor immune process, there are some other immune checkpoints, including CTLA-4, TIM3, LAG3, NKG2A, and so on, which are also recognized and participate in co-regulating immune responses with anti-PD-L1 therapy." (PMID 39900923, 2025).